MTDH (metadherin)
Diseases named in the same sentence as MTDH in open-access papers (continued):
Sharing a sentence is not in itself a finding about the gene and the disease.
cancer (205 papers, 2010 to 2025). A tumor composed of atypical neoplastic, often pleomorphic cells that invade other tissues. "SND1 and its binding partner MTDH are two proteins that are prominently implicated in cellular transformation, cancer metastasis, and drug resistance." (PMID 37973913, 2023). "SND1/MTDH are frequently overexpressed and associated with poor prognosis across many cancer types including PC22–26." (PMID 37973913, 2023). "Metadherin is a transmembrane protein which controls different pathways closely associated with cancer, such as nuclear factor-kappa B (NF-κB), Wnt/b-catenin, MAPK/ERK, PI3K/AKT, and AP-1." (PMID 34577789, 2021). "Both miR-497 and metadherin play an important role in angiogenesis which is the hallmark of cancer progression." (PMID 34577789, 2021). "We found that RKIP expression was inversely linked to the intracellular level of MTDH in cancer cells." (PMID 33802672, 2021). "Elevated MTDH expression was founded to associate with a worse overall survival and poorer immune response in patients with cancer." (PMID 34622157, 2021). "Studies had linked miR-497 and metadherin in the process of tumorigenesis and cancer progression, such as in ovarian cancer and non-small cell lung cancer." (PMID 34577789, 2021). "Several microRNA have also been found to be associated with the increased MTDH expression in different cancers." (PMID 31131259, 2019). "MTDH is involved in multiple cancer associated cellular signaling pathways, most notably in the context of this review, pro-angiogenesis and pro-metastasis pathways." (PMID 31131259, 2019). "Based on 14 studies that examined the association of MTDH with mortality of various female reproduction cancers, the pooled random effects HR was 3.647 (95% CI: 2.385–5.577, P < 0.001)." (PMID 27917902, 2016). "MTDH, the other identified target gene, is tightly relevant to carcinogenesis: it is reported to promote cancer proliferation and metastasis and be associated with poor prognosis." (PMID 27229534, 2016). "The pooled results from these studies indicated MTDH overexpression in reproduction cancers can cause a short lifespan for patients." (PMID 27917902, 2016). "An oncogenic role of MTDH gene, which encodes metadherin, has been implicated in a variety of cancer types including HCC." (PMID 26062443, 2015). "More recently an amplification of the MTDH gene encoding the protein metadherin has been associated with a promotion of metastasis formation in several types of cancer." (PMID 20822525, 2010). "Recently, many reports have demonstrated that oncoprotein MTDH is linked to the biological processes such as cancer cell survival, proliferation, apoptosis, migration, metastasis and chemoresistence." (PMID 20565850, 2010). "All these findings have implicated the role of the overexpression of MTDH in the initiation and progression of cancer." (PMID 20565850, 2010). "MTDH overexpression has been associated with increased cancer cell metastasis." (PMID 36902125, 2023). "Our study is the first investigation focusing on the associations between MTDH expression and immunotherapy response in multiple cancer cohorts, which consistently indicated that high expression of MTDH might resist cancer immunotherapy." (PMID 34622157, 2021). "Since genetic changes exert a great influence on not only gene expression but also gene function, we investigated the genetic alterations (mutation, fusion, amplification, or deletion) of the MTDH gene obtained from human subjects (n = 10,953) in the same set of the TCGA cancer studies." (PMID 33802672, 2021). "m6A RNA methylation and EMT may involve the associations of MTDH with immunotherapy resistance and cancer prognosis." (PMID 34622157, 2021). "Recent studies using cell culture or xenograft models have implicated MTDH in several cancer-related processes, including proliferation, cell death, invasion, and angiogenesis, although the underlying mechanistic understanding of MTDH in these processes remains limited to date." (PMID 32083506, 2020).
cancer (continued). "Afterwards, Metadherin (MTDH), also known as AEG-1 (Astrocyte Elevated Gene 1) and Lyric that implicated in various aspects of cancer progression and metastasis, was further identified as a direct target gene of miR-128 and its expression level was up-regulated in clinical samples as expected." (PMID 32993809, 2020). "Furthermore, altered expression, copy number and mutations of MTDH have been identified in many cancer types as reported in the cBIO database." (PMID 31131259, 2019). "Based on the association between MTDH and metastasis, we hypothesized that MTDH might prevent cancer cells from anoikis after extravasation in metastatic site." (PMID 29029495, 2017). "High MTDH expression is associated with poor prognosis in a large spectrum of cancer types." (PMID 29029495, 2017). "Although MTDH has been linked to both metastasis and resistance to chemotherapy in various types of cancers, the mechanism and biological function of MTDH is largely unknown." (PMID 21687633, 2011). "The two most highly upregulated genes were MTDH, which encodes for the transmembrane protein metadherin that is involved in multiple aspects of cancer progression, metastasis, and drug resistance, and cyclin B1 (CCNB1), suggesting that cell cycle inhibitors may be effective against these cells." (PMID 38999963, 2024). "Taken together, the downstream genes of MTDH in cancer may associate with EMT." (PMID 34622157, 2021). "Moreover, we explored the MTDH-m6A-RNA-methylation-EMT-associated gene signature in cancers." (PMID 34622157, 2021). "Moreover, metadherin promotes the expression of angiogenic factors, such as hypoxia-inducible factor 1-α and matrix metalloproteinase-9, and enhances transformation of endothelial cells to carcinoma-associated fibroblasts." (PMID 34577789, 2021). "Therefore, the overexpression of MTDH is related to drug susceptibility in some cancer cells." (PMID 25993398, 2015). "Although S-palmitoylation of MTDH has been overexpressed in early proteomic studies, its functional implications in cancer progression have remained largely unexplored." (PMID 41318030, 2025). "Astrocyte elevated gene-1/metadherin is an oncogene, which is overexpressed in many cancers, including HCC and promotes HCC development and progression." (PMID 41448428, 2025). "A recent study revealed that elevated levels of MTDH inhibit ferroptosis, and this increase in MTDH expression paradoxically made the cancer cells more sensitive to ferroptosis-inducing treatments." (PMID 41286067, 2025). "The silencing of MTDH significantly lowered proteins found in gene sets involved in cancer-related pathways such as VEGFA-VEGFR2 and EGF-EGFR signaling, which are crucial for angiogenesis and cell proliferation." (PMID 41286067, 2025). "MTDH has been identified as a target gene in various cancers, with its overexpression playing a key role in cancer development." (PMID 40104500, 2025). "MTDH has been identified to be increased in many cancers, and plays a key role in cancer progression." (PMID 38625581, 2024). "In the present study, we found that Metadherin is overexpressed in BC and is significantly correlated with individual cancer stage, age, subclasses, menopause and nodal metastasis status." (PMID 38253625, 2024). "MTDH deregulation was related to many of human cancers, and proliferation, metastasis, chemoresistance, and angiogenesis were included in MTDH-induced malignant hallmarks in cancer cells." (PMID 38625581, 2024). "Several publications have highlighted MTDH as an important target in the treatment of BC, including its role in cancer onset and progression." (PMID 36902125, 2023). "High expression of lncRNA prostate cancer non-coding RNA 1 (PRNCR1) leads to significant overexpression of MTDH through sponging miR-126-5p to promote the proliferation of cancer cells." (PMID 38152110, 2023).
cancer (continued). "It is noteworthy that given the multiple pathways interactions, oncogenic roles, and involvement in the chemoresistance of MTDH/LYRIC, there is an increased interest in investigating this molecule as a potential therapeutic target in cancer." (PMID 37711209, 2023). "It has also been reported that some biological behaviors involved in cancer progression and metastasis are influenced by Metadherin (MTDH), also known as AEG1 (Astrocyte Elevated Gene 1)." (PMID 37438760, 2023). "While the important role of SND1/MTDH in cancer is well documented, the molecular mechanisms of their function are only beginning to be understood." (PMID 37973913, 2023). "Metadherin (MTDH) enables cancer cells to adhere tightly to blood vessels and consequently reach other distant organs." (PMID 38152110, 2023). "Metadherin, commonly known as astrocyte‐elevated gene‐1 (AEG‐1), is closely related to cancer initiation and progression." (PMID 36789748, 2023). "A pluripotent oncogene known as Metadherin (MTDH, also known as AEG-1), which has been implicated in driving cancer metastasis, can directly interact with CEACAM1." (PMID 36497444, 2022). "A more direct indicator of cancer progression, MTDH is an oncogene which promotes cancer cell proliferation." (PMID 35959493, 2022). "Metadherin/astrocyte-elevated gene-1 (MTDH) (also known as astrocyte-elevated gene-1/LYRIC) is an abnormally activated oncogene found in a variety of cancers." (PMID 36133745, 2022). "Another study showed that high-expressed metadherin was helpful to cancer cell proliferation, while berberine reduced metadherin and inhibited cancer cell proliferation." (PMID 35889396, 2022). "The results thus suggest that targeting the β‐catenin‐metadherin/CEACAM1‐CCL3 positive feedback cascade holds great therapeutic potential to disrupt polyploidization of the cancer subclones that drive metastasis." (PMID 35403834, 2022). "Mechanistically, β‐catenin upregulates cancer cell surface metadherin, which communicates through CEACAM1 expressed on macrophages to produce CCL3." (PMID 35403834, 2022). "Generally, MTDH is predominantly located in the nucleus in benign tissues and cells, while it is located mainly in the cytoplasm in cancer tissues and cells." (PMID 34893064, 2021). "It is a known binder of metadherin (MTDH), a dsRNA binder and proposed oncogene overexpressed in many cancers." (PMID 34217309, 2021). "Immunosuppressive cells (such as M2 macrophages, Th2 cells, fibroblasts) positively correlated with the MTDH/m6A/EMT pathway score across diverse cancers." (PMID 34622157, 2021). "As a result, the elevated level of MTDH in cancer can lower RKIP protein through the transcriptional repression possibly together with other transcription factors." (PMID 33802672, 2021). "The expression of MTDH in cancer cells is regulated by diverse mechanisms including miRNA-mediated post-transcriptional processes." (PMID 34893064, 2021). "The expression of MTDH in cancer tissues and cells was detected by immunohistochemical staining or qRT-PCR." (PMID 34552061, 2021). "In this study, we further explored the regulatory mechanism of miR-9-3p and MTDH in promoting the toxicity of gemcitabine (Gem) on cancer cells by performing in vitro cell experiment and in vivo mouse experiment." (PMID 34552061, 2021). "First, we examined the expression profile of MTDH in cancer tissues (n = 31) obtained from human samples in the cancer genome atlas (TCGA), and the corresponding normal tissues from GEPIA." (PMID 33802672, 2021). "High expression of MTDH was discovered and validated to predict a worse overall survival for immunotherapy-naïve and immunotherapy-treated patients with cancer." (PMID 34622157, 2021). "In order to discover the significance of the comprehensive pathway connecting with MTDH, EMT, and m6A RNA methylation, we estimated the score of the pathway by z-scored their associated genes in TCGA tumors and an independent cancer immunotherapy cohort." (PMID 34622157, 2021).
cancer (continued). "AEG-1, also called MTDH, has oncogenic potential in numerous cancers and is considered a multifunctional modulator because of its involvement in developmental processes and inflammatory and degenerative brain diseases." (PMID 33440655, 2021). "First, we examined total RKIP mRNA levels in MTDH-knockdown and MTDH-overexpressing MCF-7 cancer cells using quantitative RT-PCR analysis." (PMID 33802672, 2021). "In this study, we investigated the molecular mechanism of how MTDH directs and stimulates cancer progression, and we found that the elevated level of MTDH in cancer cells suppress the transcription of the RKIP gene." (PMID 33802672, 2021). "The estimated score of CD8+ T cells, CD4+ central memory T cells (CD4+ Tcm), and Th1 cells were increased significantly in MTDH-low expression patients across diverse cancer types." (PMID 34622157, 2021). "MTDH has been confirmed to activate numerous cancer-related signalling pathways that potentially contribute to CDDP resistance." (PMID 34893064, 2021). "The 3D plot showed the mutual correlations between EMT, m6A RNA methylation, and MTDH expression in cancer." (PMID 34622157, 2021). "Mtdh1 encodes metadherin, also known as AEG-1, a downstream target of Ras and c-Myc, and MTHD1 is upregulated in many cancers." (PMID 34398873, 2021). "More clinical trials or large population cohorts are needed to validate the possible translational role of MTDH in cancer immunotherapy." (PMID 34622157, 2021). "Previous studies revealed the vital roles of MTDH in the metastasis and chemoresistance of cancer cells, uncovering the potential of MTDH as an antitumor therapeutic target." (PMID 31978894, 2020). "Uni- and multi-variate Cox regression of MTDH protein expression for cancer-specific survival (CSS) in 111 ccRCC from Peking University First Hospital." (PMID 31978894, 2020). "A further study with more focus on the MTDH-PTEN complexes in cancer immunity is therefore suggested." (PMID 32066429, 2020). "It has been reported that MTDH plays a key role in cancer therapy resistance due to its ability to maintain CSC populations." (PMID 31979093, 2020). "Metadherin has previously been shown to regulate processes important in cancer such as mRNA binding within the ER, regulation of apoptosis and regulation of c-myc expression." (PMID 31450747, 2019). "The significance of MTDH regulation of cancer growth was confirmed using miRNA-375 and MTDH knockdown experiments in HNSCC model." (PMID 31131259, 2019). "MTDH can regulate the cancer cell metastasis by actin cytoskeletal remodeling in gastric and non-small cell lung cancer." (PMID 31131259, 2019). "MTDH overexpression was documented in many types of cancer and correlates clinically to poor overall survival." (PMID 31527591, 2019). "Metadherin (MTDH), popularly called astrocyte elevated gene‐1 (AEG‐1), is significantly involved in cancer development." (PMID 30932352, 2019). "Metadherin (Mtdh), also known as lysine-rich CEACAM1 co-isolated (LYRIC)/3D3 and astrocyte elevated gene-1 (AEG-1), was initially discovered as an oncogene that is upregulated in various types of cancers, such as breast carcinoma and hepatoma." (PMID 30976056, 2019). "In vitro and in vivo chemical resistance analysis has indicated that MTDH knockdown sensitizes several different cancer cell lines to paclitaxel, doxorubicin, cisplatin, and ultraviolet radiation." (PMID 30932352, 2019). "We recently identified three T-cell epitopes within the MTDH protein supporting its potential value as a cancer vaccine target." (PMID 31131259, 2019). "Here we present an overview of the MTDH expression and function in various cancers as well as its potential as an intrinsic treatment modulating agent." (PMID 31131259, 2019). "Overexpression of MTDH is observed in a variety of cancers belonging to all biological systems, and has crucial relevance in cancer progression, including proliferation, autophagy, and chemoresistance." (PMID 30932352, 2019).
cancer (continued). "Several studies have established a bona fide role of MTDH in several hallmarks of cancer, including transformation, proliferation, evasion of apoptosis, and therapeutic resistance." (PMID 31527591, 2019). "Recently, the affected expression of metadherin (MTDH), also known as AEG-1 (Astrocyte Elevated Gene 1) and Lyric, has been implicated in various aspects of cancer progression and metastasis." (PMID 31131259, 2019). "For these reasons there is now an urgent need to determine the clinical and therapeutic significance of increased MTDH expression in cancer." (PMID 31131259, 2019). "Given that MTDH/AEG-1 expression is increased in many cancer types and proof of principle experiments support it as an effective immunotherapy target, further research is now warranted to test such treatments efficacy in advanced preclinical cancer models." (PMID 31131259, 2019). "Although the understanding of the MTDH cancer promoting mechanisms is incomplete, there is a compelling evidence that MTDH regulates multiple signaling pathways which cooperate to promote the tumorigenic and metastatic potential of transformed cells." (PMID 31131259, 2019). "As a result, we identified eight common mutated genes (EBAG9, MTDH, ATP6V1C1, OPA1, ATCL6A, BCL6, SENP5, KRAS) in the three different cancer types and used them as cross-cancer biomarkers to perform an integrative network analysis." (PMID 29459674, 2018). "Specifically, TAX treatment became more effective when MTDH expression was decreased in MCF-7 cancer cells by the blocking nuclear factor-kappa B (NF-κB) pathway." (PMID 30227879, 2018). "Whereas MTDH is slightly expressed in normal pancreatic duct, it is strongly expressed the membrane and cytoplasm of cancer cells." (PMID 29029495, 2017). "A recent study came to unravel this mechanism of action, demonstrating that MTDH protects cancer cells by interfering with the cell cycle checkpoints and initiating pro-survival cascades." (PMID 29064423, 2017). "In other cancer cells, MTDH was found to induce EMT through the activation of p38 MAPK or AKT signaling." (PMID 28107197, 2017). "MTDH has emerged as a crucial oncogene that participates in every aspect of cancer development and progression." (PMID 28107197, 2017). "In vitro studies showed that MTDH provides cancer stem cell (CSC) properties in metastatic PDAC cells and contributes to anoikis resistance with epithelial characteristics in PDAC cells." (PMID 29029495, 2017). "Each guide strand and passenger strand coordinately regulates oncogenic genes as observed in several cancers, e.g., pre-miR-145: MTDH and UHRF1; pre-miR-139: MMP11; pre-miR-150: SPOCK1." (PMID 28902136, 2017). "Only four cancer tissues (22.2%) showed higher VDAC1 expression, while 17 cancer tissues (94.4%) showed higher MTDH expression." (PMID 27229534, 2016). "Our function assays showed that knockdown of MTDH inhibited cancer cell aggressiveness and affected downstream signal pathways under the following headings: “focal adhesion”, “pathways in cancer”, “endocytosis” and “cell cycle”." (PMID 27765924, 2016). "Meanwhile MYC also transcribes MTDH expression and stimulates oncogenetic activity in cancer cells including MM." (PMID 26683226, 2016). "Among these pathways, we focused on “Focal adhesion”, “Pathways in cancer” and “Endocytosis” pathways because MTDH contributed to cancer cell migration and invasion." (PMID 27765924, 2016). "Just recently, several reports reveal that MTDH is regulated by microRNAs and involved in cancer development." (PMID 27229534, 2016). "Recent studies showed that several miRNAs control the expression of MTDH in multiple types of cancer, such as miR-375, miR-136, miR-26a and miR-145-5p." (PMID 27765924, 2016). "MTDH was identified as oncogene in multiple cancers including MM which denotes that MTDH is an intriguing therapeutic target for cancer treatment, nevertheless the MTDH inhibitors still await for further investigation." (PMID 26683226, 2016).